CLDN4 (claudin 4)
Diseases named in the same sentence as CLDN4 in open-access papers (continued):
Sharing a sentence is not in itself a finding about the gene and the disease.
benign prostatic hyperplasia (4 papers, 2008 to 2021). A non-cancerous nodular enlargement of the prostate gland. "In prostate, claudin-4 was down-regulated and claudins-2, -3, and -5 were overexpressed in prostate adenocarcinomas compared with benign prostatic hyperplasia samples." (PMID 22559840, 2012). "Benign prostatic hyperplasia glands stained primarily with a moderate intensity for claudin-4 compared with PSMA and AMACR, which stained at low intensity and negatively, respectively." (PMID 18648369, 2008). "Claudin-4, coding for an integral membrane cell-junction protein, was the most significantly (P<0.00001) upregulated marker in both primary and metastatic tumour specimens compared with benign prostatic hyperplasia at both RNA and protein levels." (PMID 18648369, 2008).
endometriosis (4 papers, 2020 to 2023). The growth of functional endometrial tissue in anatomic sites outside the uterine body. "Studies have shown lower expression of claudin-3 and claudin-4 in ectopic endometriosis tissue compared to eutopic endometrium in women with endometriosis at messenger mRNA and protein levels." (PMID 37446108, 2023). "The transcription level of CLDN4 is significantly higher in the endometrium of idiopathic infertility and minimal endometriosis, indicating that CLDN4 overexpression might be negatively linked to endometrial receptivity." (PMID 36171908, 2022). "Downregulation of claudin-3, claudin-4, and claudin-7 may contribute to the establishment of endometriosis." (PMID 36091010, 2022). "SPP1, LIF, TCN1 and CLDN4 were common to adenomyosis and healthy groups of genes, while ANXA2, EDNR8, MMP26, DEPP1, ABCC3, CDA and SLC1A1 were common to endometriosis and healthy groups." (PMID 32933042, 2020).
esophageal cancer (4 papers, 2021 to 2025). A primary or metastatic malignant neoplasm involving the esophagus. "It was also shown that Twist1 may modulate CLDN4 expression which suggests that claudin-4 is directly associated with EMT in esophageal cancer." (PMID 34822542, 2021). "TWIST1 expression has been reported to correlate with the downregulation of Claudin-4 in esophageal cancer tissues and in cell lines overexpressing TWIST147." (PMID 40204777, 2025). "Claudin-7 was reduced in LUAD, whereas claudin-3 and claudin-4 were increased in esophageal cancer." (PMID 38841188, 2024).
non-small cell lung carcinoma (4 papers, 2015 to 2025). A group of at least three distinct histological types of lung cancer, including non-small cell squamous cell carcinoma, adenocarcinoma, and large cell carcinoma. "Epithelial markers and the markers of non-small cell lung cancer (NSCLC), such as pan-cytokeratin, CAM5.2, claudin-4, CK5, p40, and CK7, in all tested cases were not expressed, and single cases showed focal weak TTF-1 and p63 expression." (PMID 40909976, 2025).
oral squamous cell carcinoma (4 papers, 2020 to 2023). "Nuclear CLDN4 is found in 39% of oral squamous cell carcinomas and 81% of oral C. perfringens-positive cases." (PMID 36982569, 2023). "In contrast, in oral squamous cell carcinoma, CLDN4 released into the cytoplasm by CPE from C. perfringens in the oral flora binds to YAP and ZO-2 and translocates into the nucleus, promoting proliferation and inducing EMT." (PMID 36982569, 2023). "When CLDN4 expression was examined in oral squamous cell carcinoma (OSCC), 22 out of 57 (39%) cases showed immunoreactivity in the nucleus." (PMID 32064037, 2020). "Treatment of human oral squamous cell carcinoma cell lines HSC3 and HSC4 with Clostridium perfringens enterotoxin (CPE), induced CLDN4 nuclear translocation to enhance epithelial-mesenchymal transition (EMT), stemness, cell proliferation and invasive ability." (PMID 32064037, 2020). "Nuclear claudin-4 (CLDN4) expression showed a stronger relation with cancer progression than the nuclear negative immunoreactivity in oral squamous cell carcinoma (OSCC)." (PMID 36362947, 2022).
pancreatic ductal adenocarcinoma (4 papers, 2017 to 2021). An infiltrating adenocarcinoma that arises from the epithelial cells of the pancreas. "A similar phenomenon was also observed in CLDN4 expression and its prognostic significance in human pancreatic ductal adenocarcinoma." (PMID 35155561, 2021). "Here, we aimed to investigate the effects of inhibiting CLDN4 in pancreatic ductal carcinomas (PDC)." (PMID 31498559, 2019). "Recent attempts relied on the use of a [111In]anti-claudin-4 mAb for diagnosis of pancreatic ductal carcinomas, or a [64Cu]-labeled CPE fragment that has been used for ovarian cancer diagnosis." (PMID 29258264, 2017). "Higher CLDN4 expression represents better outcomes in human pancreatic ductal adenocarcinoma." (PMID 35155561, 2021). "The aim of this work was the preparation and preliminary biological evaluation of peptide conjugates potentially suitable for PET-imaging of infiltrating pancreatic ductal adenocarcinoma (PDAC), using claudin-4 as a molecular target." (PMID 29258264, 2017).
pulmonary edema (4 papers, 2015 to 2024). Accumulation of fluid in the lung tissues causing disturbance of the gas exchange that may lead to respiratory failure. "Low expression of claudin-4 results in leakier tight junctions, decreased alveolar fluid clearance, and increased pulmonary oedema with mechanical ventilation." (PMID 37186068, 2023). "Wray C and colleagues demonstrated that claudin-4 suppressed air space fluid clearance and exacerbated ventilator-induced pulmonary oedema in vitro." (PMID 37186068, 2023). "Moreover, Cldn4 is also involved in resolution of pulmonary edema, while being used as indicator of pulmonary damage." (PMID 34872491, 2021).
renal cell carcinoma (4 papers, 2020 to 2025). "In renal cell carcinoma, nuclear localization of CLDN4 has been associated with epithelial-mesenchymal transition, a process known to involve a remodeling of cell-cell contacts." (PMID 40380298, 2025). "In renal cell carcinoma, EphA2/Ephrin A1 and PKCε translocate CLDN4 into the nucleus, with YAP bound and co-translocated alongside CLDN4." (PMID 36982569, 2023). "In renal cell carcinoma, when CLDN4 expression was observed in the nucleus, the cancer progressed significantly." (PMID 35418179, 2022). "In addition, PKCε induced the co-nuclear translocation of YAP and CLDN4 in renal cell carcinoma." (PMID 35418179, 2022). "Herein, we investigated the role of CLDN4 in renal cell carcinoma (RCC), focusing on CLDN4." (PMID 33172177, 2020). "In renal cell carcinoma, unlike many epithelial malignancies, CLDN4 expression level is low, but nuclear CLDN4 is observed in 2% of tumors, all of them at an advanced stage." (PMID 36982569, 2023).
sarcoma (4 papers, 2017 to 2025). A usually aggressive malignant neoplasm of the soft tissue or bone. "In our opinion Claudin-4 is helpful in the differentiation of SMARCB1 (INI1) - deficient carcinoma and sarcoma." (PMID 35864317, 2022). "A positive immunoreactivity for highly-specific non-mesothelial markers, in particular with claudin-4, tends to exclude MPM, although pulmonary sarcomatoid carcinomas and some sarcomas are negative for claudin-4." (PMID 34070888, 2021). "Across all cancer types, CLDN4 expression was generally elevated in tumour tissues relative to normal counterparts, with the exception of head and neck squamous cell carcinoma (HNSC), kidney renal clear cell carcinoma (KIRC), sarcoma (SARC) and skin cutaneous melanoma (SKCM)." (PMID 41252335, 2025).
squamous cell carcinoma (4 papers, 2008 to 2024). A carcinoma arising from squamous epithelial cells. "However, when comparing adenocarcinoma with squamous cell carcinoma, significant differences were observed in the expression of CLDN-3, CLDN-4, and CLDN-7." (PMID 38338691, 2024). "Also, we found positive immunoreactivity for MUC4 in some cases of adenocarcinoma and squamous cell carcinoma with no CEA and/or Claudin 4 expression." (PMID 29317712, 2018).
thyroid cancer (4 papers, 2013 to 2025). "In this study, we investigated the expression patterns of claudin-1 and claudin-4 in thyroid pathologies, discussed their links with the pathogenesis of thyroid cancers, and reviewed the therapeutic potential of targeting claudins in cancers." (PMID 39458944, 2024). "We reviewed the literature and summarized the previous reports to highlight the potential role of claudin-1 and claudin-4 targeted therapy in thyroid cancer." (PMID 39458944, 2024). "To highlight the potential role of claudin-1 and claudin-4 targeted therapies in thyroid cancer, we revised and summarized relevant studies published between 2019 and 2024." (PMID 39458944, 2024). "This study explored the concept of targeting claudin-1 and claudin-4 in thyroid cancer." (PMID 39458944, 2024). "Targeting claudin-1 and claudin-4 is a promising approach to managing thyroid cancers." (PMID 39458944, 2024). "Clarifying the role of claudin-1 and claudin-4 in the pathogenesis of thyroid cancers may improve our understanding of tight junction proteins’ role in early metastasis." (PMID 39458944, 2024). "Claudin-1 and claudin-4 expressions were negative in medullary carcinoma and most anaphylactic carcinoma samples, indicating tight junction loss in aggressive thyroid cancers, suggesting that the downregulation of claudins is associated with the de-differentiation of thyroid cancer." (PMID 39458944, 2024).
atopic dermatitis (3 papers, 2018 to 2020). "The protein level of CLDN1 is decreased in atopic dermatitis, whereas that of CLDN4 is increased." (PMID 31398894, 2019).
diabetes (3 papers, 2017 to 2024). "Here, we show with a number of approaches that Cldn4 in the mouse pancreatic islets is associated with regulating FS of the islets, implicating in translational research for better diabetes therapies." (PMID 31562747, 2020). "It was found that diabetes increased co-IP of WNK4 with cldn-4; these findings were confirmed by reverse IP." (PMID 28493961, 2017). "In our previous studies, we found that diabetes decreases the expression of cldn-5 in GL and cldn-2 and occldn in PT, and induces the expression of cldn-4 and -8 in DT." (PMID 28493961, 2017). "It was found that SPL treatment decreased diabetes-induced cldn-4 and -8 expressions in DT, evaluated by IF, IB and qRT-PCR." (PMID 28493961, 2017). "We provided multiple pieces of evidence for the first time that the highly expressed TJ molecule Cldn4 may be involved in regulating the FS of the pancreatic insulin‐secreting β cells with implications in translational research for better diabetes therapies." (PMID 31562747, 2020). "Thus, we suggest a previously unidentified role for Cldn4 in regulating the FS of islets, with implications in translational research for better diabetes therapies." (PMID 31562747, 2020). "In order to evaluate whether diabetes induces cldn-4 and -8 interactions in the TJ, co-immunoprecipitation (co-IP) analyzes were performed in isolated DT." (PMID 28493961, 2017). "In this study, we found that diabetes induced threonine phosphorylation of cldn-4 and -8." (PMID 28493961, 2017). "In DT, SPL diminished the increment in TJ localization, mRNA and protein expression of cldn-4 and -8 induced by diabetes, thus suggesting that ALD mediates the transcription and expression of cldn-4 and -8 under diabetic condition." (PMID 28493961, 2017). "Also, it was found that diabetes promotes WNK4 co-localization with cldn-4 and -8 in the TJ, thus suggesting that WNK4 interacts directly and phosphorylates cldn-4 and -8 on threonine residues." (PMID 28493961, 2017). "We previously reported that diabetes does not induce oxidative stress in DT, which partially explains the increased expression of cldn-4 and -8 in this segment." (PMID 28493961, 2017).
dysplasia (3 papers, 2009 to 2022). A usually neoplastic transformation of the cell, associated with altered architectural tissue patterns. "Previous studies have shown that the expression level of CLDN-4 is higher in intestinal metaplasia (IM) and dysplasia than in the normal mucosa." (PMID 35743616, 2022). "Claudin-4 expression was present in only 7(15.9%) normal gastric samples, but expression of claudin-4 in the intestinal metaplasia lesions and dysplasia lesions was 90.5% and 95.2%, respectively." (PMID 23822740, 2013). "In dysplasia the claudins Cldn2, Cldn4 and Cldn8 were significantly up-regulated, their expression ranged from 4.6–13.31-fold and 4.9–122.38-fold, when transgenic but healthy and non-transgenic lung tissue were compared, respectively." (PMID 19529782, 2009).
endotoxemia (3 papers, 2018 to 2023). "Chronic consumption of fructose (but not glucose) can induce endotoxemia in mice and gene expression of claudin-4 is reduced in vitro with the addition of fructose." (PMID 29971089, 2018).
gastric tumors (3 papers, 2020 to 2025). "Studies on claudin expression in various cancers provide heterogeneous data, though upregulation of CLDN1, −3 and −4 has been repeatedly reported for colon cancer, and up- and dysregulation of CLDN4 and −18.2 have been shown in gastric tumors." (PMID 37514167, 2023). "Several other studies have used CLDN-4 as a target for tumor therapy and showed the accumulation of anti-CLDN-4 mAbs specifically in the tumors and reduced the growth of human colorectal and gastric tumors in mice." (PMID 31952355, 2020).
gestational diabetes mellitus (3 papers, 2023 to 2025). "For example, RBM15 was observed to hinder insulin sensitivity and promote insulin resistance through m6A-mediated epigenetic suppression of CLDN4 during the development of gestational diabetes mellitus." (PMID 38765115, 2024).
inflammatory bowel disease (3 papers, 2017 to 2022). A spectrum of small and large bowel inflammatory diseases of unknown etiology. "A prior study of inflammatory bowel disease demonstrated the ability of TGFβ1 signaling inhibition to suppress CLDN4 expression." (PMID 35281827, 2022). "The intestinal proinflammatory immune factor and NF-κB could induce the decrease in claudin-1 expression inflammatory bowel disease, and BBR might regulate claudin-4 and claudin-2 expressions other than claudin-1 in claudin family." (PMID 28217099, 2017).
Insulin resistance (3 papers, 2023 to 2024). Increased resistance towards insulin, that is, diminished effectiveness of insulin in reducing blood glucose levels. "In vitro, RBM15 suppressed insulin sensitivity and increased insulin resistance through m6A-regulated epigenetic inhabitation of CLDN4." (PMID 36803098, 2023). "In this study, our data firstly revealed that RBM15 might contribute to the development of metabolic syndrome based on insulin resistance through the m6A-mediated regulation of CLDN4 in GDM offspring." (PMID 36803098, 2023).
metastatic prostate carcinoma (3 papers, 2008 to 2020). A carcinoma that arises from the prostate gland and has spread to other anatomic sites. "Especially, Cldn-4 is highly expressed in both primary and metastatic prostate cancer suggesting a potential role of Cldn-4 as a prognostic factor for advanced and metastatic prostate cancer." (PMID 33584695, 2020).
pancreatitis (3 papers, 2011 to 2024). Inflammation of the pancreas. "Similar results come from experimentally induced pancreatitis in rats where the mRNA levels of claudin 4, claudin 5 and occludin decreased due to pancreatitis induced lung injury but increased after administration of emodin, a chemical suggested to enhance epithelial barrier function." (PMID 21619599, 2011). "In pancreatitis, occludin, claudin-1 and ZO-1 are decreased, but no changes in claudin-4 have been reported; whereas E-cadherin and β-catenin are dissociated from the plasma membrane and condensed in the cytosol of acinar cells." (PMID 39030443, 2024).
Pleural effusion (3 papers, 2023 to 2025). The presence of an excessive amount of fluid in the pleural cavity. "HEG1 and Claudin-4 IHC staining together are particularly useful for differentiating reactive or malignant mesothelial cells from adenocarcinoma in pleural effusion." (PMID 40091315, 2025). "In the extensive MPE cohort, a notably increased expression of CLDN4 in cells from pleural effusion among patients diagnosed with recurrent MPE was observed, compared with the non‐recurrent group, which was also associated with a trend towards worse overall survival (OS)." (PMID 38629624, 2024).
prostate tumors (3 papers, 2006 to 2021). "Claudin-4 was present in all the metastatic prostate tumour cell lines and decreased in the order of expression, PC3, DU145, LNCaP and ALVA41." (PMID 18648369, 2008). "Our in silico and RT-PCR results are consistent with numerous previous reports showing that CLDN3 and CLDN4 are overexpressed in breast, ovarian, and prostate tumors." (PMID 16836752, 2006). "Our present study demonstrates that targeting Cldn3 and Cldn4 may be therapeutically useful for managing prostate tumors that have high Cldn3 or Cldn4 expression levels." (PMID 35006480, 2021).
thymoma (3 papers, 2017 to 2023). A neoplasm arising from the epithelial cells of the thymus. "In AB thymoma, claudin-4 was more strongly expressed in the epithelial cells surrounding the cysts in the A component." (PMID 36797681, 2023). "Several important genes associated with thymus development, such as CLDN4, FGF7 and FGF10, showed high expression in certain thymoma subtypes and TCs, suggesting their potential role in the development of TETs." (PMID 34568003, 2021). "In FDC-S diagnosis, FDCSP and SRGN showed both a good sensitivity, higher than CD23 and Claudin 4, and an extremely good specificity, evaluated on 214 controls including carcinomas, soft tissue tumors, melanomas, thymomas and interdigitating dendritic cell sarcomas." (PMID 28145886, 2017). "Similarly, claudin-4 expression was stronger in medullary islands of B1 thymoma." (PMID 36797681, 2023). "In this study, we aimed to explore the expression of thymic cortical epithelial markers (β5t, PRSS16, and cathepsin V) and medullary epithelial markers (claudin-4, CD40, and AIRE) in thymoma and TSCC and its correlation with histological classification, staging, and prognosis." (PMID 36797681, 2023).
acute myeloid leukemia (2 papers, 2023). Acute myeloid leukemia (AML) is a group of neoplasms arising from precursor cells committed to the myeloid cell-line differentiation. "For example, Hao and colleagues found that the expression of CLDN4 was abnormally increased in acute myeloid leukemia cells." (PMID 37057131, 2023). "We also discovered that a higher expression of CLDN4 is associated with poorer survival and is an independent indication of shorter disease-free survival (DFS) in patients with acute myeloid leukemia." (PMID 37057131, 2023). "In acute myeloid leukemia cells, inhibiting the expression of CLDN4 led to a significant reduction in cell proliferation as well as an increase in the rate of apoptosis." (PMID 37057131, 2023).
acute pancreatitis (2 papers, 2022 to 2023). An acute inflammatory process that leads to necrosis of the pancreatic parenchyma. "Previous study in our laboratory showed that dietary supplementation of pectin could enhance intestinal barrier function, increase the expression of Claudin-4 and Muc-2 in the cecum of piglets, and abolish the abnormal expression of ZO-1 and Occludin caused in the acute pancreatitis model." (PMID 36569061, 2022). "Bioinformatics analysis suggests that claudin-4 may be regulated by FOX3 or USF2 and plays an important role in acute pancreatitis, and the variation in claudin-4 expression in PCa and acute pancreatitis needs to be further investigated." (PMID 36959784, 2023).
atrophic gastritis (2 papers, 2019 to 2022). "In our study, more than 90% of the highly expressed CLDN-4 group showed open-type atrophy, and we considered that high expression of CLDN-4 in EGC may be linked with severe atrophic gastritis and the subsequent presence of synchronous tumors." (PMID 35743616, 2022).